SCARNA17 (small Cajal body-specific RNA 17)
Synonyms: mgU12-22/U4-8; U91
Gene: Small Cajal body-specific RNA gene on chromosome 18 (49,814,133 to 49,814,276, forward strand). Ensembl gene ENSG00000251992.
Gene Ontology:
Biological process: RNA processing
Cellular component: Cajal body; nucleolus
Homologues: Orthologues: chimpanzee SCARNA17 (100% identical), macaque SCARNA17 (96% identical), dog SCARNA17 (74% identical).